BACH1 (BACH transcriptional regulator 1)
Diseases named in the same sentence as BACH1 in open-access papers (continued):
Sharing a sentence is not in itself a finding about the gene and the disease.
ovarian carcinoma (19 papers, 2005 to 2025). A malignant neoplasm originating from the surface ovarian epithelium. "Recently a frame shift mutations in the Bach1 gene that greatly affect the risk of invasive ovarian cancer has also been identified in ovarian cancer." (PMID 22369660, 2012). "When overexpressed in colon or ovarian cancer cells, BACH1 enhanced tumor growth in transplanted mice, but metastasis was not investigated." (PMID 34339740, 2021). "In one report, the overexpression of BACH1 in human ovarian cancer cells increased the expression of VEGFC and promoted both angiogenesis and lymphangiogenesis when transplanted in mice." (PMID 34339740, 2021). "Previous studies have shown that BACH1 promotes angiogenesis by modulating VEGFC expression in ovarian cancer and colorectal cancer." (PMID 33932125, 2021). "Invasion and migration activities of PDAC cells, esophageal cancer cells, colon cancer cells, and ovarian cancer cells in vitro are reduced upon BACH1 knockdown." (PMID 34339740, 2021). "In the detachment section, BACH1 is also involved in the invasive progression of ovarian cancer at the peritoneal surface owing to its effect on EMT genes such as Snail family transcriptional repressor 2 (Slug)." (PMID 32780245, 2020). "As is ovarian cancer, BACH1 promotes PDA cell migration and invasion in part by repressing E-cadherin expression." (PMID 32780245, 2020). "Mutations in CHL1 human homologs BACH1/BRIP/FANCJ and ChlR1/DDX11 helicases collectively result in Warsaw Breakage Syndrome, Fanconi anemia, breast and ovarian cancers." (PMID 29186203, 2017). "The issue is a critical one given that mutations in the Chl1 human homologs ChlR1/DDX11 and BACH1/BRIP1/FANCJ collectively result in Warsaw Breakage Syndrome, Fanconi anemia, cell aneuploidy and breast and ovarian cancers." (PMID 29186203, 2017). "Chl1 is of further import because it is the homolog of both ChlR1/DDX11 and BACH1/BRIP/FANCJ, mutations in which result in Warsaw Breakage Syndrome and both Fanconi anemia and breast and ovarian cancers, respectively." (PMID 24086532, 2013). "The metastasis of ovarian cancer migration is promoted by BACH1 through its recruitment of high‐mobility group AT‐hook protein 2 (HMGA2) and binding to the promoters of EMT‐related genes, such as snail family transcriptional repressor 1 (SNAIL) and snail family transcriptional repressor 2 (SLUG)." (PMID 39887888, 2025). "In addition, in ovarian cancer, BACH1 boosts the metastasis of cancer cells by enhancing the expressions of Slug, Snail, and HMGA2." (PMID 34191748, 2021). "BRIP1, also known as BACH1 or FANCJ, is an essential tumor suppressor gene based on the identification of clinically relevant BRIP1 mutations in several cancers like hereditary breast and ovarian cancers and childhood cancer syndrome." (PMID 28968953, 2017). "Other studies have found that USP14 stabilises BACH1 by deubiquitination, regulating heme metabolism through the NRF2 signalling pathway and promoting cancer cell invasion in ovarian cancer." (PMID 40988122, 2025). "Previous studies reported that BACH1 induces angiogenesis and lymphangiogenesis by regulating the transcription of VEGFC to promote the expansion and aggressiveness of ovarian carcinoma." (PMID 33932125, 2021). "SNAI2 is directly activated by BACH1 in PDAC, ovarian cancer, and esophageal squamous cell carcinoma cells, suggesting that the BACH1–SNAI2 axis likely contributes to the silencing of epithelial genes." (PMID 34339740, 2021).
hepatocellular carcinoma (15 papers, 2013 to 2025). A malignant tumor that arises from hepatocytes. "In hepatocellular carcinoma, BACH1 is stimulated by lncRNA712 via sponging miR-142-3p, thereby boosting proliferation." (PMID 38321558, 2024). "Pan-cancer analysis revealed that low BACH1 expression predicts better outcomes in patients with kidney papillary cell carcinoma, lower grade glioblastoma, hepatocellular carcinoma, pancreatic adenocarcinoma, sarcoma, and thyroid carcinoma." (PMID 38321558, 2024). "For example, results from our laboratory and others have shown that BACH1 promotes the metastasis of hepatocellular carcinoma, making it a promising novel biomarker predicting a poor prognosis." (PMID 38321558, 2024). "The inhibition of BACH1 expression in porcine kidney cells and human hepatoma cells resulted in increased resistance to AFB1." (PMID 36139865, 2022). "By directly increasing PTK2 and IGF1R in hepatocellular carcinoma cells, BACH1 speeds up the development and spread of Hepatocellular carcinoma (HCC)." (PMID 36407100, 2022). "Nevertheless, the exact mechanism of BACH1 promoting growth and metastasis and its therapeutic significance in hepatocellular carcinoma (HCC) remain unclear." (PMID 35154476, 2022). "In hepatocellular carcinoma (HCC), BACH1 upregulates the expression of cell motility-related genes, such as insulin-like growth factor 1 receptor (IGF1R) and protein tyrosine kinase 2 (PTK2), to facilitate the growth and metastasis of HCC." (PMID 38321558, 2024). "One study found that reduced BACH1 and elevated HO-1 levels played critical roles in reducing the cytotoxicities of HCV proteins in hepatocellular carcinoma (HCC) cells." (PMID 37228820, 2023). "Recent studies have found that BACH1 promotes the advancement of several cancers, including clear-cell renal cell carcinoma, esophageal squamous cell carcinoma, hepatocellular carcinoma (HCC), and pancreatic cancer." (PMID 37444447, 2023). "Also the circRNA BACH1, a circRNA highly expressed in hepatocellular carcinoma (HCC), inhibits the translation of p27kip mRNA by facilitating HuR translocation to the cytoplasm." (PMID 33202605, 2020). "Similarly, the reduction of UBR7 levels mediated by methyltransferase ALKBH5 reduces the transcription of Keap1, which in turn upregulates the Nrf2/BACH1/HK2 pathway, promoting tumorigenesis in hepatocellular carcinoma by targeting glycolysis." (PMID 38321558, 2024). "The treatment of Hepa1 hepatoma cells with TBK1 inhibitors did not affect the amount of BACH1 mRNA." (PMID 38673728, 2024). "Besides, TRG-AS1 is overexpressed in hepatocellular carcinoma (HCC) cells, where it enhances HCC cell proliferation, migration, EMT, and invasion by sponging miR4500 to regulate the expression of BACH1." (PMID 34136488, 2021).
lung adenocarcinoma (14 papers, 2020 to 2025). A carcinoma that arises from the lung and is characterized by the presence of malignant glandular epithelial cells. "In the Keap1-mutated lung adenocarcinoma, activated Nrf2 (encoded by Nfe2l2) stabilizes Bach1 expression that further promotes invasion and metastasis of lung tumors." (PMID 33809182, 2021). "Previous studies have reported that the NRF2/HO-1 pathway improve BACH1 stabilization in lung adenocarcinoma cells." (PMID 40263598, 2025). "At the transcriptional level, BACH1 can promote lung adenocarcinoma cell metastasis by directly activating ITGA2 transcription, and KLF7 has been shown to regulate ITGA2 expression to maintain oral cancer stem cell properties." (PMID 40940943, 2025). "In conclusion, our study confirmed the vital role of BACH1 in the prognosis of early-stage lung adenocarcinoma." (PMID 35035660, 2022). "Our research confirmed that BACH1 was an important predictor of prognosis in early-stage lung adenocarcinoma." (PMID 35035660, 2022). "We utilized bioinformatics approach such as the Cancer Genome Atlas (TCGA) and Gene Expression Omnibus (GEO) database to explore the role of BACH1 expression in the prognosis of early-stage lung adenocarcinoma." (PMID 35035660, 2022). "In this pioneering study, we confirmed that BACH1 was an important prognostic factor for early-stage lung adenocarcinoma by establishing a BACH1-based prognostic model that incorporated BACH1 expression and clinical characteristics." (PMID 35035660, 2022). "In this study, we established a BACH1-related prognostic model to predict overall survival (OS) of early-stage lung adenocarcinoma." (PMID 35035660, 2022). "We aimed to explore the value of BACH1 in predicting the overall survival (OS) of early-stage (stages I-II) lung adenocarcinoma." (PMID 35035660, 2022). "Overexpression of FBXO22 has been reported to suppress the Bach1‐driven metastasis of lung adenocarcinoma and promote nuclear tumor suppressive factor PTEN downregulation to play a tumor-promoting role in colorectal cancer." (PMID 33622332, 2021). "BACH1 is a vital and independent predictor in early-stage lung adenocarcinoma." (PMID 38321558, 2024). "BACH1 was an independent prognostic factor for lung adenocarcinoma." (PMID 35035660, 2022). "Integrated analyses of RNA-seq and ChIP-seq to access BACH1 targets using lung adenocarcinoma identified that BACH1 activates transcription of hexokinase 2 (HK2) and Glyceraldehyde 3-phosphate dehydrogenase (GAPDH) at their promoters as a transcriptional activator." (PMID 33809182, 2021). "In recent reports, BACH1 showed that it suppresses mitochondrial oxidative phosphorylation, but enhances aerobic glycolysis in TNBC or lung adenocarcinoma." (PMID 35406740, 2022). "The functional role of BACH1 for cancer metabolism was not validated only by gene expression analysis of the patient data cohorts such as The Cancer Genome Atlas (TCGA) including breast, lung adenocarcinoma, and pancreas ductal adenocarcinoma, but by follow-up experiments." (PMID 33809182, 2021).
melanoma (12 papers, 2015 to 2025). A malignant, usually aggressive tumor composed of atypical, neoplastic melanocytes. "We conclude that a broad range of antioxidants accelerate melanoma migration and metastasis and that BACH1 is functionally linked to melanoma metastasis in vivo." (PMID 36774779, 2023). "Thus, two unbiased genomics analyses identify BACH1 as a gene and protein associated with antioxidant administration in human malignant melanoma and other cancer cells." (PMID 36774779, 2023). "•BACH1 is functionally linked to melanoma metastasis in vivo." (PMID 36774779, 2023). "Herein, we reported a novel PLK1/BACH1 axis as a resistant mechanism in the treatment of melanoma with Vemurafenib." (PMID 41284701, 2025). "To investigate the regulatory role of PLK1 on BACH1 in melanoma, we assessed the protein stability of BACH1 and found its protein level significantly reduced in melanoma cells under the PLK1 inhibition." (PMID 41284701, 2025). "This study uses a mouse model of melanoma to show that PLK1 stabilizes BACH1, which transcriptionally regulates genes involved in cancer metabolism and metastasis, independently of the cell cycle." (PMID 41284701, 2025). "Genomics analyses revealed that the transcription factor BACH1 is activated following antioxidant administration and knockout of Bach1 in mouse melanoma cells reduced lymph node and liver metastasis in xenograft mouse models." (PMID 36774779, 2023). "But on the other hand, knockout of Bach1 significantly reduced melanoma cell metastasis to lymph nodes and liver in in vivo experiments—which means that BACH1 can be functionally tied to metastasis in several cancer forms." (PMID 36774779, 2023). "To define the functional importance of BACH1 in melanoma metastasis, we used CRISPR/Cas9 approaches to inactivate Bach1 in mouse B16–F1 melanoma cells." (PMID 36774779, 2023). "Consistently, in the same model, or in cells exposed to fructose, melanoma cells increased HO-1 expression through the degradation of Bach1 and the induction of NRF2." (PMID 35740068, 2022). "Taken together, our results demonstrate that PLK1 promotes melanoma development and progression through BACH1, while the depletion of BACH1 could abolish the PLK1-induced phenotypes in melanoma." (PMID 41284701, 2025). "Moreover, when BACH1 was abolished, there was a significant increase in cellular ROS levels observed in both human and mouse melanoma cells, coupled with a reduction in antioxidant molecules NADPH and GSH." (PMID 41284701, 2025). "We subsequently examined the protein expression of BACH1 in both mouse melanoma cells and tumors." (PMID 41284701, 2025). "In mouse and human melanoma cells with PLK1 overexpression, BACH1 demonstrated a significantly more stable phenotype and an extended half-life." (PMID 41284701, 2025). "In this study, we found that PLK1 regulates melanoma’s metabolic reprogramming, metastasis, and drug resistance by stabilizing BTB domain and CNC homolog 1 (BACH1)." (PMID 41284701, 2025). "Specifically, BACH1 and VEGFC expression are significantly higher in samples from melanoma patients clinically diagnosed with lymph node metastatic spread, as compared with those with primary tumors." (PMID 32132179, 2020). "Similarly, upon Hemin treatment, an inducer of BACH1 degradation, PLK1 overexpression led to more stabilized BACH1 in the melanoma cells." (PMID 41284701, 2025). "Moreover, the PLK1/BACH1 axis confers resistance to Vemurafenib, a BRAFV600E inhibitor, in melanoma." (PMID 41284701, 2025). "Importantly, the knockdown of BACH1 abolished the phenotypes elicited by PLK1 in both human and melanoma cells, with reduced glycolysis, increased OXPHOS, inhibited metastasis, and resensitization to Vemurafenib treatment." (PMID 41284701, 2025). "Interestingly, we found that BACH1 expression positively and significantly correlates with the expression of VEGFC in human melanoma and LUAD cancer progression." (PMID 32132179, 2020).
melanoma (continued). "According to our prior observations that the PLK1/BACH1 axis contributes to the Vemurafenib resistance in melanoma, we investigated whether the PLK1 inhibitor Volasertib, in combination with Vemurafenib, could achieve improved therapeutic efficacy in melanoma." (PMID 41284701, 2025). "However, it is not yet clear whether BACH1 is activated in malignant melanoma cells and contribute to metastasis." (PMID 36774779, 2023). "The results demonstrated that HPF treatment induced HO-1 expression in melanoma cells, which was not dependent on the NRF-2 transcription factor but was potentially regulated by its transcriptional repressor BACH-1." (PMID 37507910, 2023).
pancreatic cancer (12 papers, 2021 to 2025). "For instance, high expression of BACH1 that regulate EMT is linked with poor prognosis of pancreatic cancer." (PMID 33928036, 2021). "We reported recently that TBK1 maintains the amounts of BACH1 mRNA and protein in pancreatic cancer cells." (PMID 38673728, 2024). "In renal and pancreatic cancers, BACH1 has been reported to inhibit the proliferation and migration." (PMID 36670112, 2023). "For example, BACH1 inhibits EMT by decreasing vimentin expression in pancreatic cancer but promotes EMT by increasing vimentin expression in esophageal cancer." (PMID 37228820, 2023). "Recently, the CRISPR/Cas9 mediated Bach1 knockout in a pancreatic cancer cell line (AsPC1) shows novel Bach1 targeted genes such as CLDN3, CLDN4, PKP2, CHD1, and FOXA1, a subset of genes that enhance the metastasis of tumor cells." (PMID 36139853, 2022). "Notably, recent work demonstrates that sustained NRF2 activation can stabilise BACH1 by inducing HO-1, thereby inhibiting BACH1 degradation and enhancing the metastatic potential, particularly in lung and pancreatic cancers." (PMID 41154512, 2025). "It indicated that BACH1 may have different effects on EMT-related genes in pancreatic cancer cell lines of different origins." (PMID 37228820, 2023). "Further mechanistic studies are needed to elucidate the function of BACH1 in pancreatic cancer." (PMID 37228820, 2023). "We analyzed the mRNA expression data from TCGA using the GEPIA database (Gene Expression Profiling Interactive Analysis) and found that the expression of BACH1 and TBK1 are positively correlated in pancreatic cancer." (PMID 36009179, 2022). "For instance, in human pancreatic cancer cells, BACH1 binds the AIFM2/FSP1 gene, though Bach1 does not bind Aifm2/Fsp1 or regulate its expression in murine cells." (PMID 39025451, 2024).
colorectal cancer (11 papers, 2016 to 2026). A primary or metastatic malignant neoplasm that affects the colon or rectum. "HOXB8 occupies and activates the transcription of the BACH1 gene with BACH1 itself and interacts with BACH1 to cause a transcriptional cascade, thereby enhancing colorectal cancer invasion." (PMID 38321558, 2024). "In colorectal cancer, BACH1 is upregulated by circ_0087862 via sponging miR-142-3p to facilitate proliferation of colorectal cancer cells." (PMID 38321558, 2024). "In colorectal cancer, BACH1 facilitates the expression of CXCR4 as demonstrated by TCGA dataset analysis, western blotting, and immunohistochemistry." (PMID 38321558, 2024). "In colorectal cancer, the high expression of BACH1 is positively correlated with a high clinicopathological stage." (PMID 38321558, 2024). "HOXB8 interacts with BACH1 and activates BACH1 itself as well as its target genes transcription in colorectal cancer." (PMID 35154476, 2022). "Investigations in colorectal cancer and melanoma have shown that the heterodimer of BACH1 and MAFG recruits DNA methyltransferase DNMT3b to silence genes, including tumor suppressor genes." (PMID 34339740, 2021). "The mRNA levels of Hmox1, Nrf2, Keap1, and Bach1 in the tumor and normal tissues of 84 subjects with colorectal cancer (CRC) were determined by real-time polymerase chain reaction." (PMID 27999449, 2016). "BACH1 collaborates with HOXB8 in metastasis of colorectal cancer." (PMID 34339740, 2021). "The cytotoxic effect was evaluated for a combination of rotenone, an inhibitor of mitochondrial respiration, and two different inhibitors of Bach1 transcription factor in the prostate cancer cell lines (PC3 and Du145) and colorectal cancer (HT-29 and HCT-116) in a kinetic mode." (PMID 41912851, 2026).
prostate carcinoma (11 papers, 2011 to 2026). A carcinoma that arises from epithelial cells of the prostate gland. "In agreement with our earlier observations, LISA-derived prediction showed that decreased DNA methylation in prostate cancer was associated with distinct chromatin remodeling enzymes, including BACH1 and PCGF6, in AA men." (PMID 38566104, 2024). "This study provides evidence that S.C effectively suppresses tumor progression and induces ferroptosis in prostate cancer cells by targeting ROS/USP47/BACH1/HMOX1 axis." (PMID 38195593, 2024). "More specifically, our study revealed that S.C represses tumor progression and induces ferroptosis in prostate cancer cells by targeting the ROS/USP47/BACH1/HMOX1 axis." (PMID 38195593, 2024). "This study provides evidence that S.C effectively suppresses tumor progression and induces ferroptosis in prostate cancer cells by targeting the ROS/USP47/BACH1/HMOX1 axis." (PMID 38195593, 2024). "This study found that S.C induces ferroptosis by targeting the ROS/USP47/BACH1/HMOX1 axis in prostate cancer cells." (PMID 38195593, 2024). "Furthermore, ablation of BACH1 in human colon carcinoma or in prostate cancer cells prevents cell growth, migration, and invasion in vitro, decreasing the expression of its main metastasis-related genes, MMP1, let-7a, and CXCR4." (PMID 32132179, 2020). "In particular, RegNetB identified the regulators PAX4, BACH1, BACH2, MAZ and TAF8 as playing a central role in this prostate cancer gene expression data set." (PMID 21682879, 2011). "ROS, especially H2O2, reduce SLC7A11 and GPX4 expression in cervical cancer and prostate cancer; additionally, ROS stimulate BTB domain and CNC homolog 1 (BACH1) degradation by decreasing the expression of ubiquitin carboxyl-terminal hydrolase 47 (USP47), which can deubiquitinate BACH1." (PMID 39584140, 2024).